PRMT1 (protein arginine methyltransferase 1)
Diseases named in the same sentence as PRMT1 in open-access papers (continued):
Sharing a sentence is not in itself a finding about the gene and the disease.
asthma (4 papers, 2016 to 2025). "PRMT1 is involved in the inflammatory response associated with asthma." (PMID 41256732, 2025). "PRMT1 influences the processing of miRNAs associated with asthma in lung epithelial cells." (PMID 41256732, 2025). "Beside novel information on the cell type specific conditions leading to allergic asthma, our data may provide the basis for three novel therapeutic and diagnostic targets in asthma as PRMT1, PIAS1 and RKIP." (PMID 26911452, 2016). "The role of PRMT1 in asthma encompasses various aspects, including airway remodeling, miRNA processing, and the inflammatory response." (PMID 41256732, 2025). "The expression of PRMT1 was cell type specific and responded to several well-known asthma triggers including TGF-β1 and IL-4." (PMID 31979396, 2020). "In the context of asthma, methylation of histone H3 is mainly catalyzed by PRMT1, which is a novel mediator of airway remodeling in asthma." (PMID 31979396, 2020). "As PRMT1 is induced by different cytokines in lung epithelial cells and fibroblasts, and participates in both inflammation and remodeling in asthma, we investigated the link between these two cell types on PRMT1 expression." (PMID 26911452, 2016). "The possible role of PRMT1 in the pathogenesis of asthma is described in more detail below." (PMID 31979396, 2020). "This might explain the loss of microRNA-19a and the subsequently deregulated constitutive expression of PRMT1 in mesenchymal airway wall cells of patients with moderate to severe asthma." (PMID 31979396, 2020). "Thus PRMT1 expression in structural lung cells in asthma can be considered as potential target for new therapeutic intervention." (PMID 26911452, 2016). "Dysregulation of PRMT1 activity and expression is significantly associated with the pathogenesis of various immune‐mediated diseases, including rheumatoid arthritis (RA), systemic lupus erythematosus (SLE), asthma, and chronic graft‐versus‐host disease (cGVHD)." (PMID 41256732, 2025). "TGF-β1 stimulated the expression of the epi-genetic acting protein arginine methyltransferase 1 (PRMT1), which is controlled by several asthma relevant stimuli including HSP60." (PMID 31979396, 2020). "In particular, the expression of PRMT1 was significantly higher in the AIPI model, implying putative involvement of PRMT1 in asthma." (PMID 27041824, 2016).
cervical carcinoma (4 papers, 2017 to 2023). A carcinoma arising from either the exocervical squamous epithelium or the endocervical glandular epithelium. "It has been reported that PRMT1 expression maybe a potential predictive marker for neoadjuvant chemotherapy treatment in patients with locally advanced cervical cancer." (PMID 34522232, 2021). "HIF1A transcription is downregulated by protein arginine methyltransferase 1 (PRMT1), a protein whose transcription is regulated by SP1 in human Hela cervical carcinoma and human HEK293T embryonic kidney cells." (PMID 37998757, 2023).
head and neck squamous cell carcinoma (4 papers, 2023 to 2025). A squamous cell carcinoma that arises from any of the following anatomic sites: lip and oral cavity, nasal cavity, paranasal sinuses, pharynx, larynx, and salivary glands. "PRMT1 drives carboplatin resistance and tumor progression in head and neck squamous cell carcinoma (HNSCC) through a novel, methyltransferase‐independent mechanism." (PMID 40270464, 2025). "The expression of both PRMT5 and PRMT1 has been tested in multiple head and neck squamous cell carcinoma (HNSCC) and A549 cells where OHKC (immortalized normal oral keratinocytes) and DOK (dysplastic oral keratinocytes) cells serve as normal and dysplastic cell lines." (PMID 38709899, 2024). "More importantly, PRMT1 expression was negatively correlated with the infiltration of CD8+ T cells and macrophages in BRCA, skin cutaneous melanoma (SKCM), and head and neck squamous cell carcinoma." (PMID 37193698, 2023).
idiopathic pulmonary fibrosis (4 papers, 2012 to 2025). Idiopathic pulmonary fibrosis (IPF) is a nonneoplastic pulmonary disease that is characterized by the formation of scar tissue within the lungs in the absence of any known cause. "In addition, PRMT1 has been proven to be associated with pulmonary fibrosis." (PMID 40612681, 2025). "For example, elevated expression of PRMT1 has been observed in the fibroblasts derived from idiopathic pulmonary fibrosis, and it has the ability to enhance IPF fibroblasts motility." (PMID 40612681, 2025). "Observed that expression of PRMT1 was increased in IPF (idiopathic pulmonary fibrosis) lung fibroblasts and IPF lungs and in lungs of bleomycin-treated mice, and PRMT1 knockdown or inhibition of PRMT activity reduced IPF fibroblast motility." (PMID 36817133, 2023). "In vitro studies revealed that ANGII may induce PRMT1 expression and endothelial cell activation, resulting in the generation of reactive oxygen species (ROS), key players in the establishment/progression of pulmonary fibrosis in animal models and possibly in human IPF." (PMID 23202904, 2012).
liver disease (4 papers, 2019 to 2025). "The discrepancy between expression and activity indicates a multifaceted role for PRMT1 in hepatic disorders." (PMID 41256732, 2025). "Although there is compelling evidence indicating the involvement of PRMT1 in a variety of liver diseases, the precise physiological role of PRMT1 in hepatocytes remains not fully comprehended." (PMID 39063139, 2024). "This function of PRMT1 might be important in further progression of liver disease induced by alcohol." (PMID 31235809, 2019).
lymphoma (4 papers, 2013 to 2023). A malignant (clonal) proliferation of B- lymphocytes or T- lymphocytes which involves the lymph nodes, bone marrow and/or extranodal sites. "Type I PRMT inhibitors, which mainly target the predominant PRMT1 in vivo, induce cell death and arrest proliferation in leukemia and lymphoma cell lines and reduce their ability to form tumors in xenotransplantation models." (PMID 37310381, 2023). "In contrast, both lung tumor and lymphoma tissue express higher levels of protein arginine methyltransferase 1 (PRMT1), a relatively abundant methyltransferase, at 300 and 432 TPM respectively." (PMID 23800116, 2013). "We conclude that PRMT1 is regulated in a MYC- and mTORC1-dependent manner in BCL cells to sustain lymphoma cell proliferation and also to prevent their differentiation." (PMID 37310381, 2023).
myocardial hypertrophy (4 papers, 2018 to 2025). "To determine the function of PRMT1 in cardiac hypertrophy and cardiac fibrosis, we performed loss-of-function and gain-of-function experiments by transfection with si-PRMT1 and PRMT1 overexpression plasmid." (PMID 37951845, 2023). "In an isoproterenol‐induced animal model of myocardial hypertrophy, PRMT1 expression was significantly downregulated." (PMID 41256732, 2025). "As a result, CID2818500 exacerbated ISO-induced hypertrophy and fibrotic responses, indicating that suppression of methylation activity of PRMT1 triggered cardiac hypertrophy and cardiac fibrosis." (PMID 37951845, 2023). "PRMT1 can reduce calcium/calmodulin‐dependent protein kinase II (CaMKII) activity by methylating arginine residues (e.g., R9 and R275) of CaMKII, hence inhibiting arrhythmia and cardiac hypertrophy resulting from excessive CaMKII activation." (PMID 41256732, 2025). "Besides, to investigate the function of methylation activity of PRMT1 in cardiac hypertrophy and cardiac fibrosis, a pharmacological inhibitor that specifically targeted to PRMT1, named CID2818500, was employed in NRCMs." (PMID 37951845, 2023). "Taken together, PRMT1 and its methylation protect against cardiac hypertrophy and fibrosis." (PMID 37951845, 2023). "Furthermore, we found that PRMT1 protected against cardiac hypertrophy and fibrosis in vitro." (PMID 37951845, 2023).
pancreatic ductal adenocarcinoma (4 papers, 2020 to 2025). An infiltrating adenocarcinoma that arises from the epithelial cells of the pancreas. "In vivo, the loss of PRMT1 oligomerization leads to decreased global ADMA levels in pancreatic ductal adenocarcinoma (PDAC) cells and inhibits PDAC tumor growth." (PMID 40675804, 2025). "High levels of PRMT1 are associated with beneficial prognosis of pancreatic ductal adenocarcinoma patients." (PMID 37005412, 2023). "Furthermore, we demonstrate that the oligomeric state is essential for PRMT1’s role in facilitating the proliferation of pancreatic ductal adenocarcinoma (PDAC) cells." (PMID 40675804, 2025). "Here, the authors use functional genomics screens and identify PRMT1 as a vulnerability in pancreatic ductal adenocarcinoma, and further show that PRMT1 regulates RNA metabolism and coordinates expression of genes in cell cycle progression, maintaining genomic stability and tumour growth." (PMID 34330913, 2021).
cardiomyopathy (3 papers, 2018 to 2023). A disease of the heart muscle or myocardium proper. "Several recent studies revealed PRMT1-knockout mice hearts demonstrated various structural alterations which were similar to morphological and functional characteristics in human cardiomyopathies." (PMID 37951845, 2023).
chondrosarcoma (3 papers, 2020 to 2024). A malignant cartilaginous matrix-producing mesenchymal neoplasm arising from the bone and soft tissue. "A recent study identified YAP nuclear accumulation as a consequence of LATS1 inactivation by protein arginine methyltransferase 1 (PRMT1) as an independent bad prognostic factor in chondrosarcoma." (PMID 32326412, 2020). "PRMT1 has been identified as a positive regulator of YAP1 activity in chondrosarcoma." (PMID 38444414, 2024).
clear cell renal cell carcinoma (3 papers, 2019 to 2023). "In another study in clear cell renal cell carcinoma, PRMT1 was shown to be suppressed by the novel PRMT1 inhibitor DCPT1061 both in vivo and in vitro." (PMID 36710341, 2023). "Background and Objective: Epigenetic alterations are common events in clear cell renal cell carcinoma (ccRCC), and protein arginine methyltransferase 1 (PRMT1) is an important epigenetic regulator in cancers." (PMID 33859753, 2021).
colorectal adenocarcinoma (3 papers, 2020 to 2025). The most common type of colorectal carcinoma. "Stratified analysis of circ-PRMT1 expression in colorectal adenocarcinoma subgroups further validated its association with adverse clinical outcomes." (PMID 40724932, 2025). "Elevated circ-PRMT1 expression was associated with significantly shorter DFS and OS in colorectal adenocarcinoma patients." (PMID 40724932, 2025). "Colorectal adenocarcinoma patients with circ-PRMT1 overexpression were shown to have significantly lower DFS probabilities (p < 0.001) compared to patients with lower circ-PRMT1 levels." (PMID 40724932, 2025). "In this study, we showed the prognostic significance of circ-PRMT1 overexpression in colorectal adenocarcinoma to be an independent molecular predictor of poor DFS and OS." (PMID 40724932, 2025). "Our study identifies circ-PRMT1 as a clinically significant predictor of colorectal adenocarcinoma progression, with overexpression detected in 83.7% of tumors compared to matched non-cancerous tissues." (PMID 40724932, 2025). "In accordance with these findings, receiver operating characteristic (ROC) curve analysis demonstrated that circ-PRMT1 expression may successfully distinguish colorectal adenocarcinoma from normal colorectal tissue (AUC = 0.73, 95% CI = 0.66–0.80, p < 0.001)." (PMID 40724932, 2025). "Furthermore, low circ-ABCC1 expression was associated with tumor growth and disease progression, while the overexpression of circ-PRMT1 in colorectal adenocarcinoma has very recently been shown to predict recurrence and poor OS, similarly to circ-CCT3." (PMID 41153715, 2025). "Additionally, the unfavorable prognostic value of circ-PRMT1 overexpression was observed in OS analysis, which revealed that colorectal adenocarcinoma patients with circ-PRMT1 overexpression had significantly poorer OS (p < 0.001)." (PMID 40724932, 2025). "In this study, we thoroughly examined whether the expression levels of circular transcripts of the protein arginine methyltransferase 1 (PRMT1) gene can predict the prognosis of patients diagnosed with colorectal adenocarcinoma, the most frequent type of CRC." (PMID 40724932, 2025). "Hence, a highly sensitive quantitative PCR (qPCR) assay was developed and applied to quantify circ-PRMT1 expression in cDNAs from 210 primary colorectal adenocarcinoma tissue specimens and 86 paired normal colorectal mucosae." (PMID 40724932, 2025). "Next, we examined any correlation existing between circ-PRMT1 expression and the DFS and/or OS of colorectal adenocarcinoma patients." (PMID 40724932, 2025). "Furthermore, the stratification of patients based on TNM staging revealed that higher circ-PRMT1 levels were significantly related to shorter DFS and OS intervals, particularly in patients with colorectal adenocarcinoma of TNM stage II or III." (PMID 40724932, 2025). "In summary, this original research study provides evidence that circ-PRMT1 overexpression represents a promising molecular biomarker of poor prognosis in colorectal adenocarcinoma, not depending on other established prognostic factors such as TNM staging." (PMID 40724932, 2025). "Moreover, higher circ-PRMT1 expression was correlated with poorer disease-free survival (DFS) and worse overall survival (OS) in colorectal adenocarcinoma patients." (PMID 40724932, 2025).
diabetic nephropathy (3 papers, 2017 to 2023). "Another study reports that PRMT1 induces ER stress and epithelial‐mesenchymal transition in renal tubular epithelial cells and apoptosis, thereby facilitating diabetic nephropathy." (PMID 37525933, 2023). "In support of this study, demonstrated that PRMT1 induces ER stress and epithelial-mesenchymal transition in renal tubular epithelial cells and contributes to diabetic nephropathy." (PMID 36817133, 2023). "The results from both the cultured cells and the animal model suggest that PRMT1 expression is involved in the progression of diabetic nephropathy." (PMID 28671608, 2017). "Increased PRMT1 expression in proximal tubule cells has been reported to be critical to the progression of diabetic nephropathy." (PMID 28671608, 2017). "Strategies to decrease PRMT1 expression or reduce its enzymatic activity could be used to prevent the exacerbation of diabetic nephropathy." (PMID 28671608, 2017). "Additionally, apoptosis of podocytes and epithelial–mesenchymal transition (EMT) during diabetic nephropathy were suppressed by arginine methyltransferase inhibitor 1 (AMI‐1), a selective inhibitor for PRMT1." (PMID 37525933, 2023). "In another report, high, lipid-induced PRMT1 expression was also demonstrated to mediate apoptosis in mesangial cells via the PERK and ATF6 pathways, and inhibition of PRMT1 expression can delay the progression of diabetic nephropathy by suppressing the AGE-RAGE-mediated rise in ADMA." (PMID 36817133, 2023).
diffuse large B-cell lymphoma (3 papers, 2022 to 2023). "A completed phase I clinical trial with PRMT1 (GSK3368715) inhibitor was reported to inhibit cancer cell growth in patients with advanced solid tumors and diffuse large B cell lymphoma (DLBCL)." (PMID 37568815, 2023). "We evaluated the anti-tumor effect of inhibiting PRMT1 using GSK3368715, the only type I PRMT inhibitor currently in a phase I clinical trial for diffuse large B-cell lymphomas and solid tumors (NCT03666988)." (PMID 35053470, 2022).
myelodysplastic syndrome (3 papers, 2022 to 2025). A clonal hematopoietic disorder characterized by dysplasia and ineffective hematopoiesis in one or more of the hematopoietic cell lines. "Besides, high PRMT1 expression has been associated with adverse outcomes in myelodysplastic syndrome (MDS)." (PMID 37558663, 2023). "Moreover, another recent study has shown that the pharmacological inhibition of PRMT1 enhances megakaryocytic differentiation in the context of myelodysplastic syndrome (MDS)." (PMID 36358861, 2022). "Given the succinate accumulation, we expect that the HIF1α complex will be stabilized, leading to pseudohypoxia phenotypes in cells with elevated PRMT1 expression, akin to those seen in patients with myelodysplastic syndromes (MDS)." (PMID 40801789, 2025).
sarcoma (3 papers, 2021 to 2025). A usually aggressive malignant neoplasm of the soft tissue or bone. "For example, circTBC1D14, which is significantly up-regulated in triple-negative breast cancer, physically interacts with fused in sarcoma, altering its subcellular localization through protein arginine methyltransferase 1-associated transfer of fused in sarcoma." (PMID 40028033, 2025). "As a first indicator for a potential relevance of PRMT1 and PRMT5 in ES, we queried the R2 platform for PRMT1 and PRMT5 mRNA expression focusing on the Filion dataset which includes ES alongside other fusion-positive sarcomas." (PMID 40823091, 2025). "As expected, NMR analysis of the methylation-free recombinant RG/RGG model proteins cold-inducible RNA-binding protein (CIRBP) and RNA-binding protein fused in sarcoma (FUS) revealed that ADMA and MMA are detectable in recombinant proteins after incubation with PRMT1 and the methyl donor SAM." (PMID 35475236, 2021).
steatosis (3 papers, 2019 to 2024). Increased lipid within the cytoplasm of cells. "Immunostaining analysis demonstrated that hepatic expression of PRMT1 protein was lower in the ones with steatosis than those with lower liver fat content." (PMID 35401831, 2022). "PRMT1 knockout mice on control liquid diet (pair-fed) showed a mild steatosis phenotype." (PMID 31235809, 2019). "Consistent with our findings with HFD-fed mice, hepatic mRNA levels of both PRMT1 and PGC-1α were lower in obese patients with steatosis as compared to the obese subjects with low liver fat content." (PMID 35401831, 2022). "Consistent with these publications, we demonstrated that PGC-1α is an obligatory downstream effector of PRMT1 that mediate hepatic FAO capacity and subsequent protective effects of overexpressing PRMT1 against HFD-induced steatosis." (PMID 35401831, 2022).
viral infection (3 papers, 2011 to 2024). "As a result of this, myeloid-specific PRMT1 knockout mice are more susceptible to viral infection." (PMID 35705491, 2022). "We identify protein arginine N-methyltransferase 1 (PRMT1) as an important factor in viral infection of primary human cervical cells." (PMID 39386465, 2024). "Protein arginine methylation is important in viral infection and replication, as well as in cytokine signalling, and a related arginine methyltransferase, PRMT1, regulates herpes simplex replication via methylation of the ICP27 viral gene." (PMID 22254144, 2011).
alcohol (2 papers, 2019 to 2025). "Other factors known to promote PRMT1 expression include IL4, TXNIP and PDGF18,53,54, however their role in alcohol pathogenesis is not yet evaluated." (PMID 31235809, 2019).
alcoholic liver diseases (2 papers, 2019 to 2025). A disorder caused by damage to the liver parenchyma due to alcohol consumption. "Future studies are necessary to determine the potential of inducing PRMT1 in the livers of patients with alcoholic liver disease." (PMID 31235809, 2019).
anemia (2 papers, 2019 to 2025). A reduction in the number of red blood cells, the amount of hemoglobin, and/or the volume of packed red blood cells. "The results indicated that deletion of PRMT1 results in anemia and leukopenia, reducing terminal erythroid and lymphocyte differentiation." (PMID 31853216, 2019). "Overall, PRMT1 deletion in adult mice leads to anemia and leukopenia, thereby disrupting normal hematopoiesis." (PMID 31853216, 2019).